DKK1 (dickkopf Wnt signaling pathway inhibitor 1)
Diseases named in the same sentence as DKK1 in open-access papers (continued):
Sharing a sentence is not in itself a finding about the gene and the disease.
periodontitis (continued). "However, in Dkk-1 conditional knock-out mice with periodontitis, TCF-7 expression remained at control level." (PMID 31921182, 2019). "In conclusion, GCN5 plays a protective role in periodontitis through acetylation of DKK1 and applying drugs targeting GCN5, such as aspirin, could be a new approach for periodontitis treatment." (PMID 27216891, 2016). "Targeting sclerostin and DKK1 could be an attractive adjuvant strategy for periodontitis treatment." (PMID 36297683, 2022). "Despite the high levels of Dkk-1 in animals with periodontitis, there was no change after the treatments, indicating that neither LiCl nor Mon has Dkk-1 as a target." (PMID 41294202, 2025). "However, murine models of periodontitis investigating the direct effects of statins on Wnt pathways and DKK-1 levels showed reduced statin-mediated DKK-1 expression levels, which is in accordance with our results in humans." (PMID 38541234, 2024). "A period of 6 months’ statin intake is probably not sufficient for this severe (Stage III) periodontitis with the ability of losing teeth and advanced (Stage IV) periodontitis with serious potential of losing teeth and dentation, in order to significantly lower DKK-1 levels." (PMID 38541234, 2024). "However, the results of this study do not suggest that the levels of DKK1 in CF or serum are good predictors of CAL in patients who have eRA and periodontitis." (PMID 31703715, 2019).
esophageal squamous cell carcinoma (13 papers, 2010 to 2025). Esophageal squamous cell carcinoma (ESCC) is a type of esophageal carcinoma (EC) that can affect any part of the esophagus, but is usually located in the upper or middle third. "In surgically resected esophageal squamous cell carcinoma, patients with both CKAP4 and DKK1 positivity showed significantly worse overall survival and RFS than those negative for both biomarkers." (PMID 40282454, 2025). "For instance, in esophageal squamous cell carcinoma (ESCC), the DKK1 and CKAP4 interaction is considered one of the key mechanisms driving ESCC cell proliferation and tumor formation." (PMID 37835450, 2023). "Abnormal expression of DKK1, which is regulated by DKK1-CKAP4 pathway, predicts the poor prognosis of esophageal squamous cell carcinoma (ESCC)." (PMID 33541291, 2021). "DKK1 knockdown decreased FOXM1 expression and vice versa in PDAC and esophageal squamous cell carcinoma (ESCC) cells." (PMID 34117362, 2021).
lung adenocarcinoma (13 papers, 2016 to 2025). A carcinoma that arises from the lung and is characterized by the presence of malignant glandular epithelial cells. "This suggests that high DKK1 expression may be associated with poorer patient prognosis, underscoring its potential utility as a predictive marker in lung adenocarcinoma." (PMID 39766765, 2024). "In contrast to lung adenocarcinoma, survival analysis of the TCGA lung squamous cell carcinoma (LUSC) dataset revealed that the expression levels of BIRC3, CXCL5, DKK1, FOSL1, and MYC exhibited limited association with patient survival." (PMID 39858622, 2025). "For instance, circ_0000527/miR-98-5p/XIAP facilitates the malignant progression of retinoblastoma cells, and circ_0018414/miR-6807-3p/DKK1 impedes the tumor development in lung adenocarcinoma." (PMID 34421997, 2021). "Univariate and multivariate Cox analyses of DKK1 expression with overall survival (OS) among lung adenocarcinoma (LUAD) patients." (PMID 34899842, 2021). "At present, there are fewer studies on the role of Dikkopf1 (DKK1) in lung adenocarcinoma." (PMID 37752538, 2023). "In addition, STAT1-induced upregulation of LINC00467 promotes the proliferation and migration of lung adenocarcinoma cells by epigenetically silencing DKK1 to activate Wnt/beta-catenin signaling pathway." (PMID 33996559, 2021). "Several initiated signaling pathways, including linc00467/miR-20b-5p/cyclin D1 pathway and STAT1-induced upregulation of linc00467 promoted lung adenocarcinoma progression through epigenetically suppressing dickkopf WNT signaling pathway inhibitor 1 to activate Wnt/β-catenin signaling." (PMID 34713767, 2021). "DKK1 overexpression in lung adenocarcinoma has been reported to promote tumor growth and, interestingly, has been linked to resistance to anti-EGFR therapy, allowing speculation on a possible role of DKK1 in EGFR downstream activation." (PMID 39795613, 2025). "The expression levels of AREG, BIRC3, DKK1, EREG, FOSL1, MYC, and PLAU are negatively correlated with the survival ratio, and are significantly higher in the TSPX-low lung adenocarcinoma samples, compared to TSPX-high lung adenocarcinoma samples." (PMID 39858622, 2025). "DKK1 can be considered as a potential prognostic marker and a novel target for immunotherapy of lung adenocarcinoma." (PMID 37752538, 2023). "Taken together, our results suggest that TSPX may suppress the development and/or progression of lung adenocarcinoma by downregulating AREG, BIRC3, DKK1, EREG, FOSL1, MYC, and PLAU, which could exacerbate lung adenocarcinoma, and upregulating the tumor suppressor CACNA2D2." (PMID 39858622, 2025).
breast tumors (12 papers, 2007 to 2025). "We find DKK1 to be expressed by tumor cells and cancer-associated fibroblasts (CAFs) in patient samples and orthotopic breast tumors, and in bone." (PMID 39885132, 2025). "DKK1 is expressed by cancer-associated fibroblasts (CAFs) in orthotopic breast tumors and patient samples, and at higher levels by bone cells." (PMID 38659818, 2024). "Metastatic lung and breast tumors also seem to be able to evade immune detection by secreting the Wnt inhibitor DKK1 in an autocrine manner and elevated levels of DKK1 appear to be associated with worse prognosis in OG cancer." (PMID 32748171, 2020). "To further identify which cell populations express DKK1, we analyzed a single-cell RNAseq dataset from 26 primary human breast tumors, including 11 ER+, 5 HER2+, and 10 TNBC (GSE17607834)." (PMID 39885132, 2025). "To assess expression of DKK1 at tumor site, we analyzed a single-cell RNA seq dataset from 26 primary human breast tumors, including 11 ER+ (Luminal A or B), 5 HER2+, and 10 triple-negative breast cancers (TNBC) (GSE17607830)." (PMID 38659818, 2024). "DKK1 has been found preferentially expressed in hormone resistant breast tumours and tumours with poor prognosis." (PMID 24178749, 2014). "Furthermore, DKK1 expression was significantly higher in human bone metastatic tumor samples (n = 27) compared with primary breast tumor samples (n = 73) by IHC staining." (PMID 34847079, 2022). "In primary breast tumours, methylation frequencies of SFRP1, SFRP2, SFRP5 and DKK1 were 40, 77, 71 and 19%, respectively." (PMID 18283316, 2008). "We observed statistically significant preferential DKK1 expression in hormone receptor-negative (ER−/PR−) breast tumours." (PMID 17245340, 2007). "In the SQ breast tumors, we observed significantly upregulated mRNA levels of the Oct3/4 regulatory network, including ONSS, and several other PTFs, including Nanog, Sall4, Sox2, Sox4, FoxA2, Gata6, Zic2 and HoxB7, as well as Oct3/4 isoform B, polycomb suppressors Bmi1, EzH2, Amigo and Dkk1." (PMID 37298091, 2023).
chronic kidney disease (12 papers, 2014 to 2025). Impairment of the renal function secondary to chronic kidney damage persisting for three or more months. "Serum levels of DKK1 were positively associated with faster progression to end-stage renal disease." (PMID 40564142, 2025). "Growing evidence suggests that circulating Wnt signalling inhibitors such as DKK-1 and sclerostin may crucially contribute to the pathogenesis of chronic kidney disease-associated bone mineral disorder (CKD-MBD)." (PMID 27313945, 2016). "We found a significant increase in sclerostin and DKK-1 in the PMWCNT-instilled group, supporting the theory that PMWCNTs can initiate chronic kidney disease-associated bone and mineral disorder through the inhibition of Wnt signaling." (PMID 37112600, 2023). "We analyzed serum sclerostin and DKK1 in 308 patients across the stages of chronic kidney disease (kDOQI stage 1–2 n = 41; CKD stage 3 n = 54; CKD stage 4–5 n = 54; hemodialysis n = 100; peritoneal dialysis n = 59) as well as in 49 healthy controls." (PMID 28493902, 2017). "Thus, canonical Wnt signaling inhibitors, such as sclerostin and DKK-1, are presumably negative regulators of AS; indeed, in several studies, serum sclerostin was significantly increased in chronic kidney disease patients with intensive vascular calcification." (PMID 33923139, 2021). "Although the biological relevance of circulating protein measurements has not been fully elucidated, several clinical studies showed altered sclerostin and DKK-1 concentrations in metabolic bone diseases, in type 1 and 2 diabetes mellitus and in patients with chronic kidney disease (CKD)." (PMID 32640551, 2020). "However, DKK1 can attenuate calcium deposition and the expression of RUNX2 in calcified aortas from chronic kidney disease in a similar manner to Cdon39." (PMID 36609601, 2023). "In addition, in animal models of CKD-MBD (chronic kidney disease-mineral bone disease) there is an increased renal production of Wnt inhibitor family members and higher levels of circulating DKK1, sclerostin, and secreted klotho." (PMID 25369286, 2014).
endometrial cancer (12 papers, 2012 to 2025). Primary or metastatic malignant neoplasm involving the endometrium (mucous membrane that lines the endometrial cavity). "Among all the differential methylated genes, DKK1 has been shown to be a novel biomarker for endometrial carcinoma." (PMID 27556923, 2016). "The aim of the present study was to determine the role of DKK1 in endometrial carcinoma (EC) cell invasion and migration using RNA interference (RNAi) technology." (PMID 24137406, 2013). "DKK1 was highly expressed in benign endometrial tissue and downregulated in endometrial cancer." (PMID 26366420, 2015). "In human Ishikawa endometrial cancer cells, MET treatment (60 μM) decreased cell numbers and elicited distinct temporal changes in ESR1, KLF9, PGR, PGR-B, KLF4, DKK1, and other tumor biomarker mRNA levels." (PMID 32046384, 2020). "Activation of the Wnt signaling pathway via alteration of the APC, Axin, CTNBB1, Wnt ligands, Wnt inhibitors Dickkopf3 (DKK3) and Dickkopf1 (DKK1), or the secreted Frizzled-related proteins may be a key driving event in the development of endometrial cancer." (PMID 34068065, 2021). "A new in vivo study conducted in mice showed that E-MSCs but not AT- or UC-MSCs, could suppress malignant endometrial cancer through inhibition of the Wnt/β-catenin signaling pathway by secreting high levels of Dickkopf-related protein 1 (DKK1)." (PMID 37626848, 2023). "Interestingly, upon reviewing gene expression profiles obtained from progressive and non-progressive endometrial cancer, a number of inhibitors of Wnt/β-catenin signaling were indeed found to be down-regulated in progressive disease (DKK1, DKK4 and WIF1)." (PMID 22295114, 2012).
liver cirrhosis (12 papers, 2014 to 2023). "The optimal diagnostic cut-off value for DKK1 was 550.93 ng/L in a 2017 Chinese study, and the percentage of plasma DKK1 was significantly higher in the HCC group than in the HBV-related liver cirrhosis, CHB, and healthy controls (p < 0.05)." (PMID 36901717, 2023). "We found that DKK-1 serum levels were significantly lower in patients with liver cirrhosis, and that they correlated with serum markers of liver function, such as albumin, bilirubin, and platelets." (PMID 36230730, 2022). "The presence of liver cirrhosis was a factor influencing DKK-1 levels in serum in our cohort." (PMID 36230730, 2022). "Theme of this study was to check the promoter hypermethylation of cancer related target genes (SFRP2 & DKK1) in HCV infected chronic hepatitis, liver cirrhosis and HCC patients and compare that with infection free normal livers." (PMID 24947038, 2014). "DKK1 antibody effectively corrects renal osteodystrophy, while PRI-724, an inhibitor of CBP/β-catenin, inhibits the activation of hepatic astrocytes and delays the progression of liver cirrhosis." (PMID 34980884, 2022). "Our results showed no relation between Child-Pugh classification and neither serum DKK1 nor AREG levels in patients with liver cirrhosis or HCC." (PMID 31649806, 2019). "Plasma DKK1 level and the percentage of TEMs in peripheral CD14+CD16+ monocytes from HCC patients (n = 82), HBV-related liver cirrhosis (LC) patients (n = 29), chronic hepatitis B (CHB) infected patients (n = 28) and healthy volunteers (n = 31) were analyzed by ELISA and flow cytometry." (PMID 28902891, 2017).
renal fibrosis (12 papers, 2014 to 2025). A final common manifestation of a wide variety of chronic kidney diseases characterized by glomerulosclerosis and tubulointerstitial fibrosis. "All of these results suggested that the elevated levels of DKK1 in the glomeruli were associated with renal fibrosis." (PMID 37108841, 2023). "In particular, DKK1 expression in the renal tissues of the 5/6 Nx rats was strongly correlated with renal fibrosis, and the knockdown of DKK1 by DKK1-AS remarkably attenuated the CKD-associated phenotypes." (PMID 37108841, 2023). "It is noteworthy that in an established age‐associated kidney fibrosis model, the administration of DKK1, a specific Wnt inhibitor, and the mitochondrial‐targeted antioxidant mitoQ also protect mitochondrial functions, reduce cellular senescence, and retard renal fibrosis." (PMID 31318148, 2019). "DKK-1 can increase the expression of profibrotic factors in mesangial cells in a hyperglycemic model and induce renal fibrosis in streptozotocin-induced diabetic rats." (PMID 40422877, 2025). "Downregulation of DKK-1 expression was shown to decrease renal fibrosis in a streptozotocin-induced diabetic model of rats." (PMID 40422877, 2025). "Based on the IHC staining results, we found that the expression levels of DKK1 in the glomeruli were positively correlated with renal fibrosis." (PMID 37108841, 2023). "A previous report demonstrated that overexpression of DKK-1 attenuates β-catenin-induced renal fibrosis-related gene expression." (PMID 35565995, 2022). "DKK1 inhibits fibroblast-specific protein 1, collagen I, and fibronectin, which subsequently reduces renal fibrosis in obstructed kidneys." (PMID 36012674, 2022). "In conclusion, KLF10 mediated DKK-1 expression played a pivotal role in high-glucose-induced renal fibrosis." (PMID 35565995, 2022). "The quantification of renal fibrosis also demonstrated DKK1 or mitoQ mitigated age‐related fibrotic lesions in an established disease state." (PMID 31318148, 2019). "Despite the importance of DKK1/Wnt/β-catenin signaling in renal fibrosis, the upstream regulatory signaling that regulates DKK1 expression and Wnt/β-catenin signaling activation remained unclear." (PMID 27460630, 2016). "However, two other studies presented that delivering a DKK1 gene or recombinant DKK1 protein in a mouse model of unilateral ureteral obstruction (UUO) or adriamycin-induced nephropathy attenuated renal fibrosis." (PMID 37108841, 2023). "Due to the complicated involvements of different renal cell types and infiltrating immune cells in renal fibrosis, we propose that DKK1 may positively regulate β-catenin accumulation by dynamic cell-cell activities via some unknown mechanisms." (PMID 37108841, 2023). "Furthermore, DKK-1 represses fibroblast-specific protein 1, type I collagen, and fibronectin and subsequently attenuates renal fibrosis in obstructed kidney." (PMID 35565995, 2022). "The immunofluorescence staining for fibronectin and PDGFRβ and Sirius red staining indicated that treatment with DKK1 or mitoQ could ameliorate renal fibrosis in d‐gal‐treated mice." (PMID 31318148, 2019). "Wnt signaling has been implicated in the pathogenesis of renal fibrosis based on the findings that expression of Wnt ligands is upregulated in fibrotic kidneys, and inhibition of Wnt signaling using DKK-1, sFRP4 or paricalcitol can reduce renal fibrosis in mice." (PMID 26092126, 2015). "Therefore, increased plasma DKK-1 levels may reflect renal fibrosis induced by dysregulation of the Wnt/β-catenin signaling pathway." (PMID 40422877, 2025). "In addition to glomerular mesangial cells, the DKK1-mediated signaling may play an important role in different renal cell types, especially tubular epithelial cells, to promote renal fibrosis (tubulointerstial fibrosis)." (PMID 37108841, 2023). "However, the mechanism of action of DKK1 in renal fibrosis remains questionable." (PMID 36012674, 2022).
renal fibrosis (continued). "All members of the WNT protein family (except WNT5b, WNT8b, and WNT9b), β-catenin, Dkk-1, FZD, fibronectin, and MMP-7 were upregulated in the UUO model of renal fibrosis." (PMID 24465439, 2014). "The inactivation signals expressed by a high gene expression of Sost and Dkk1 may possibly reflect the negative feedback triggered by the kidney to prevent renal fibrosis and Ca deposits." (PMID 36986200, 2023).
Stroke (12 papers, 2012 to 2024). Sudden impairment of blood flow to a part of the brain due to occlusion or rupture of an artery to the brain. "Admission serum levels of DKK-1 in patients with acute coronary syndrome have been reported to be associated with major adverse cardiac events (MACEs), a composite of cardiovascular death, myocardial infarction (MI), or stroke." (PMID 36291617, 2022). "In the present study we investigated whether the BTMs sclerostin, OPG, OPN, OC and DKK-1 could be useful as biomarkers to predict increased risk of new fractures, new cardiovascular events or mortality in a cohort of elderly patients with fractures, stroke and volunteers." (PMID 38644839, 2024). "Our results indicate that ectopic DKK1 induction aggravates infarct and oedema sizes as well as well as impaired motor functions after stroke." (PMID 34915908, 2021). "For this purpose, TOPGAL reporter mice and inducible DKK1 mice will be used to dissect DKK1 role in regulating canonical Wnt pathway throughout injury and repair upon stroke." (PMID 34915908, 2021). "In the current study the levels of circulating DKK1 were significantly higher in patients with stroke compared with controls." (PMID 30496210, 2018). "Serum levels of OPG, OPN, DKK1, and sclerostin were much higher in stroke patients compared to controls." (PMID 30496210, 2018). "While DKK1 is a prognostic marker for cancer progression, it is also elevated in various neurological disorders including stroke, Parkinson's and AD." (PMID 29643768, 2018). "Although DKK1 levels have been shown to increase, its implication in stroke pathobiology and therapy remains unknown." (PMID 34915908, 2021). "Interestingly, Dickkopf-1 (DKK1), a secreted inhibitor of the pathway, has been shown to be induced after stroke in patients and animal models." (PMID 34915908, 2021). "A recent study enrolled a large number of acute ischemic stroke patients (3,178 patients), and a poor outcome was defined as modified Rankin scale score >2 at 1 year after stroke; the data showed that circulating DKK‐1 was an independent predictor for 1‐year poor outcome." (PMID 32324340, 2020). "One study found clearly increased serum levels of sclerostin and DKK-1 (also of OPG and OPN) in patients with stroke compared with volunteers." (PMID 38644839, 2024). "Patients with a stroke or fracture had higher serum levels of OPN, OPG and DKK-1 but lower levels of OC at baseline compared with healthy volunteers." (PMID 38644839, 2024). "Serum levels of sclerostin, DKK1, OPG and OPN were significantly higher in patients with stroke compared with controls." (PMID 30496210, 2018). "Importantly, pharmacological neutralization of DKK1 using WAY262611 improved structural and functional recovery after stroke." (PMID 34915908, 2021). "Both studies did not detect any correlation between Scl or Dkk1 levels and stroke severity or outcome." (PMID 33071819, 2020).